SMCR2 (Smith-Magenis syndrome chromosome region, candidate 2)
Synonyms: TCONS_00025215
Gene: Long non-coding RNA gene on chromosome 17 (17,674,026 to 17,677,688, reverse strand). Ensembl gene ENSG00000223979.
Diseases named in the same sentence as SMCR2 in open-access papers:
SMCR2 is named in the same sentence as 2 diseases in open-access papers, as found by Europe PMC text mining. Sharing a sentence is not in itself a finding about the gene and the disease. The quoted sentences say what the papers report.
Smith-Magenis syndrome (1 paper, 2019). Smith-Magenis syndrome (SMS) is a complex genetic disorder characterized by variable intellectual deficit, sleep disturbance, craniofacial and skeletal anomalies, psychiatric disorders, and speech and motor delay. "We have restored the official and standardized names, LINC01970 and SMCR2 (Smith-Magenis syndrome Chromosome Region, candidate 2), for the two lncFASN and lncSREBF1 genes respectively." (PMID 31752679, 2019).
thyroid (1 paper, 2021). "Captured downregulated lncNRAs also included annotated transcripts not yet associated with neurodevelopment, such as LINC01918 and AL139393.2, implicated in thyroid and medulloblastoma carcinoma, respectively, as well as SMCR2, also known as lncSREBF1, which plays a role in lipid metabolism." (PMID 33445654, 2021).